BRAF (B-Raf proto-oncogene, serine/threonine kinase)
Diseases named in the same sentence as BRAF in open-access papers (continued):
Sharing a sentence is not in itself a finding about the gene and the disease.
cancer (continued). "The findings of the present study have important biological and therapeutic implications for other BRAF V600E-harboring human cancers as well." (PMID 27863429, 2017). "Although some conflicts exist regarding the relationship between BRAF mutation and clinicopathological characteristics of PTC, BRAF mutation has been reported to be a risk factor for local recurrence and cancer-specific mortality in several studies." (PMID 28687736, 2017). "Due to the function described in the literature and because of being part of COSMIC’s cancer gene census list, BRAF was an especially interesting candidate." (PMID 28683819, 2017). "Our work sheds new light on BRAF, a crucially important gene in human cancer, by unveiling the repertoire of its mRNA and protein variants." (PMID 28454577, 2017). "A comprehensive genomic profiling study across 12 different cancer types identified BRAF-fusions in 0.3% of the 20,573 pediatric and adult tumors." (PMID 29156677, 2017). "As previously alluded to, the presence of GLUT1 receptors on BRAF and KRAS mutated cells promotes this prooxidant effect of vitamin C in cancer cells." (PMID 28791253, 2017). "Surprisingly, MutSigCV performed poorly for these genes since only two of these genes (EFGR and BRAF) were significant in MutSigCV for any cancer type." (PMID 28426665, 2017). "Although inhibitors of the downstream effectors such as RAF and MEK exhibit good therapeutic efficacies in BRAF mutant melanoma cells, most cancer cells are resistant to the single inhibitor treatments." (PMID 28002807, 2017). "In contrast, a handful of studies have focused on the specific alterations of miRNA expressions in BRAF-mutant cancer of other organs." (PMID 29115941, 2017). "For a better understanding of cancer cell proliferation, it is important to understand the meaning of BRAF and protein kinase." (PMID 28303522, 2017). "Mechanisms of cancer cells resistance to Vemurafenib can be established through two major mechanisms: ERK signaling activation in presence of the BRAF inhibitor and activation of parallel pro-survival pathways." (PMID 29113311, 2017). "These mutant KRAS or BRAF-driven cancers show a poorer response to chemotherapy and are negatively indicated for treatment with EGFR inhibitors." (PMID 28640835, 2017). "Remarkably, we did not observe a significant survival association with other well-known cancer genes, such as PIK3CA (lowest p = 0.007, q = 0.5 in UCEC), BRAF (lowest p = 0.028, q = 0.98 in KIRP), and FBXW7 (lowest p = 0.018, q = 0.99 in MELA-AU)." (PMID 28240231, 2017). "Coexistence of enhancer of zeste homolog 2 (EZH2) and BRAF gene aberrations has been described in many cancer types." (PMID 29202777, 2017). "Receptor tyrosine kinase (RTK) signaling pathways are frequently activated in cancer cells due to mutations of RTKs and/or their downstream signaling proteins such as KRAS and BRAF." (PMID 28002807, 2017). "Like CRCs with BRAF mutations, KRAS-mutated carcinomas had an increased frequency of the mucinous feature." (PMID 28583095, 2017). "The RKO cell line most closely resembles primary cancers of the serrated pathway as it is BRAF mutant, MSI and CIMP high." (PMID 27661107, 2016). "At the 17q22 RNF43 locus, BRAF mutant/MSS cancers had significantly more frequent deletion events (at 18/33, 54.5%) than BRAF wild type cancers (4/18, 22.2%; p=0.04)." (PMID 27661107, 2016). "Within BRAF, p.V600E is the most frequent mutation; it constitutively activates RTK signaling pathways and is prevalent in various cancers." (PMID 27529619, 2016). "Inhibition of autophagy protected cancer cells from the cytotoxic effects of selective BRAF inhibitors, in part, by promoting apoptosis in the presence of selective BRAF inhibitors." (PMID 26750638, 2016).
cancer (continued). "Using a random forest classifier, we quantitatively dissected the parameters contributing to BRAF AS cancer frequencies." (PMID 26744778, 2016). "Common ZNRF3 frameshift mutations were seen at P313 (C5 deletion) and G604 (G6 deletion) with 3 of each seen in BRAF mutant/MSI cancers." (PMID 27661107, 2016). "A recent study suggests that the mechanism by which MEK is activated in RAS-versus BRAF-mutant cancers is different, thus explaining the different responses in different systems." (PMID 27096871, 2016). "These cancers develop due to the paradoxical activation of MAPK signaling in BRAF wild-type cells with upstream activation of RAS when treated with BRAF inhibitors." (PMID 27713119, 2016). "In BRAF mutant/MSI cancers with normal staining for β-catenin, 21/33 (63.6%) also maintained normal RNF43 staining compared to only 4/23 (17.4%) BRAF mutant/MSS cancers (P<0.001)." (PMID 27661107, 2016). "Overall, β-catenin was more likely to be nuclear in BRAF wildtype compared to BRAF mutant cancers (27/28, 96.4% versus 36/92, 39.1%, P<0.0001)." (PMID 27661107, 2016). "Approximately half of all BRAF mutant serrated pathway cancers will methylate the mismatch repair gene MLH1 and develop microsatellite instability (MSI), whilst the remainder are microsatellite stable (MSS)." (PMID 27661107, 2016). "RNF43 and ZNRF3 had lower transcript expression in BRAF mutant compared to BRAF wildtype cancers and less cytoplasmic protein expression in BRAF mutant/MSI compared to other subtypes." (PMID 27661107, 2016). "This screening assay is anticipated to improve the efficiency of cancer therapy by identifying patients who required BRAF V600 inhibitors to preserve EGFR-mediated responses." (PMID 27094161, 2016). "Immunohistochemical staining was performed to detect presence of RNF43 protein expression for 63 BRAF mutant/MSI, 37 BRAF mutant/MSS and 44 BRAF wild type cancers from the formalin fixed series." (PMID 27661107, 2016). "Within the BRAF mutant cell lines, the mRNA expression levels of 30 genes in core cancer pathways are negatively correlated with drug sensitivity to PLX4720 (adjusted p < 0.05)." (PMID 26916442, 2016). "From a clinical perspective, the appreciation of discrepant responses amongst BRAF mutant cancers has highlighted the need for additional therapeutic strategies." (PMID 26942566, 2016). "We first illustrated the effect of individual hotspot mutations in BRAF, KRAS and NRAS on the sensitivity of cancer cells treated by MEK inhibitors (PD-0325901 and AZD6244)." (PMID 27356755, 2016). "For example, cancer cells with a BRAF mutation exhibited significantly increased sensitivity to PLX4720, a BRAF inhibitor that decreases the ectopic activity of the ERK signaling pathway." (PMID 26916442, 2016). "BRAF mutant cancers were predominantly present in the proximal colons of females and displayed the methylator phenotype more commonly than BRAF wild type cancers." (PMID 27661107, 2016). "Less is known about the rapid homeostatic adaptations that occur within the first few hours or days following the initiation of treatment and that allow the cancer cells to survive initial inhibition of BRAF." (PMID 26673621, 2016). "This likely reflects the higher RNF43 mutation rate in MSI cancers and therefore the inability to upregulate RNF43 in response to elevated Wnt signal, as is common in BRAF wild type cancers." (PMID 27661107, 2016).
cancer (continued). "Various cancer-related genes were also differentially expressed significantly, including BRAF, BRCA2, VEGFA, VEGFB, RET, PIK3CA, CTNNB1 and GNAS." (PMID 27350898, 2016). "This study demonstrated that RTKs are frequently coexpressed in cancer cell lines even in “kinase-addicted” cells, such as those with HER2 amplification or BRAF mutation." (PMID 27655711, 2016). "Analysis revealed significantly higher expression for both RNF43 and ZNRF3 in BRAF wild type compared to BRAF mutant cancers and normal colorectal mucosa samples (p<0.0001 for both genes)." (PMID 27661107, 2016). "Of note, up to 30% of patients treated with BRAF inhibitors develop RAS driven cancers such as squamous cell carcinomas, colon cancer or leukemia." (PMID 27200346, 2016). "Patients with BRAF mutant/MSI cancers presented at significantly older ages compared to both MSS subtypes." (PMID 27661107, 2016). "In a compendium of datasets from recent cancer sequencing projects, 0.6% of samples showed a CRAF mutation (up to 4% for a single cancer type) and 4.3% a BRAF mutation (up to 58% for a single cancer type) (as of Nov." (PMID 27273450, 2016). "Accordingly, epidermal growth factor receptor (EGF-R) inhibitors appear to provide synergy with BRAF inhibitors in multiple BRAF-mutant cancers." (PMID 26942566, 2016). "It is reasonable to believe that all patients with BRAF-mutant cancer would benefit from treatment with BRAF inhibitors." (PMID 27520988, 2016). "All other cancer drugs in the same cluster have different known or canonical targets (BRAF/CRAF-dabrafenib, sorafenib, vemurafenib, DNA methyltransferase- azacitidine)." (PMID 26954019, 2016). "The presence of RNF43 mutations was examined in 54 BRAF mutant/MSI, 33 BRAF mutant/MSS and 79 BRAF wild type cancers." (PMID 27661107, 2016). "This was observed in the majority of BRAF wildtype cancers where elevated cytoplasmic RNF43 staining was also observed, likely as a futile attempt to dampen the Wnt signal by RNF43-mediated degradation of the Frizzled receptor." (PMID 27661107, 2016). "We discuss two cases of hubs that are strongly involved in cancer: BRAF and JAK2, both with phenotypic pathogenic mutations occurring in ordered regions and affecting the disorder content of distal sites in the domain." (PMID 26322316, 2015). "The example of dabrafenib and trametinib moreover shows that compounds that target the same subset of cancer cells (i. e., BRAF-mutant) can act synergistically." (PMID 26018524, 2015). "While mutations in KRAS, BRAF, PIK3CA, and EGFR were found in cancer types expected, there were also several instances of actionable mutations identified in diseases for which these mutations have not been well characterized." (PMID 26015395, 2015). "PRDM5 was methylated in 77/214 (36.0%) BRAF mutant cancers compared to 4/122 (3.3%) BRAF wild type cancers (p < 0.0001)." (PMID 25613750, 2015).
cancer (continued). "It is important to note that even responders to anti-EGFR therapy routinely develop secondary resistance during anti-EGFR therapy, often by selection of KRAS/NRAS or BRAF-mutant clones arising from a RAS-wildtype cancer." (PMID 26299805, 2015). "PRDM5 protein expression was substantially down-regulated in both BRAF mutant and wild type cancer cohorts (92/97,95% and 39/44,89%)." (PMID 25613750, 2015). "Only when stratified for MSI status, was a correlation observed with a higher rate of nuclear beta-catenin in PRDM5 methylated compared to unmethylated BRAF mutant/MSI cancers (13/21, 62% vs 12/38, 32%) (p = 0.03)." (PMID 25613750, 2015). "The BRAF inhibitor vemurafenib lacks efficacy in this cancer, due to a feedback regulatory mechanism resulting in high EGFR activity." (PMID 26018524, 2015). "In cases with wild-type KRAS, BRAF and PIK3CA a number of cancer-associated genes representing potential drivers were identified (for example, STK11, GNAS, CHEK2 and RB1)." (PMID 25855536, 2015). "The PentaPanel platform assesses single nucleotide polymorphisms in 56 hotspots of the 5 most clinically relevant cancer genes, KRAS, NRAS, BRAF, EGFR and PIK3CA for a total of 221 detectable mutations." (PMID 26435479, 2015). "Increasing studies revealed that deregulation of miRNAs was responsible for abnormal expression of human BRAF in many cancers." (PMID 25977643, 2015). "Promising results from BRAF V600E inhibition have also been seen in patients with various other cancers harboring BRAF V600E." (PMID 25794135, 2015). "RAS and RAF gene mutations have been considered potential markers of sensitivity to MEK inhibition largely due to the constitutive activation of MEK seen in BRAF mutant cancer cells and to a lesser extent in KRAS mutant cells." (PMID 26404261, 2015). "BRAF mutant cancers had significantly more frequent PRDM5 promoter methylation than BRAF wild type cancers (77/214,36% vs 4/122,3%; p<0.0001)." (PMID 25613750, 2015). "This pathway is often dysregulated in human cancers, frequently due to activating mutations of the KRAS, NRAS, or BRAF genes." (PMID 26498038, 2015). "Further studies to characterize the BRAF mutation and MAPK pathway dysregulation in canine cancer will benefit both human and veterinary oncology." (PMID 29061943, 2015). "BRAF pathway plays an important role in tumorigenesis in NSCLC,BRAF inhibitors, vemurafenib and dabrafenib have shown only modest efficacy in BRAF-V600E mutant cancers." (PMID 25706985, 2015). "Nuclear beta-catenin as a surrogate of Wnt pathway activation was present in 39% (36/92) BRAF mutant cancers which was significantly lower than the rate observed in BRAF wild type cancers at 86% (36/42) (p < 0.0001)." (PMID 25613750, 2015). "PTC is a cancer entity that has been associated with abnormal RAS-ERK signaling and is further characterized by a high frequency of BRAF V600E mutations." (PMID 26065894, 2015). "PRDM5 methylation was found to be an early event with progressive acquisition in BRAF mutant cancers of the serrated pathway." (PMID 25613750, 2015). "We achieved robust raw CT values for both small and large RNAs, including RNAs important for cancer research such as BRAF and KRAS, as well as specific miRNAs like let-7a and miR-142-3p that have previously been reported to be specifically enriched in EVs." (PMID 26317354, 2015). "The discovery of BRAF mutations and MAPK pathway dependence of human cancers led to the therapeutic strategy targeting BRAF/MAPK pathway." (PMID 29061943, 2015). "FDA-approved companion diagnostics used in the treatment of adult cancers have been based on DNA sequence (for example, BRAF V600E/K) or on protein expression (for example, HER2/neu)." (PMID 25720842, 2015).
cancer (continued). "We found the PRDM5 promoter region was substantially methylated in BRAF mutant cancers of the serrated pathway whereas minimal levels of methylation were detected in the BRAF wild type cancers of the traditional pathway." (PMID 25613750, 2015). "One human cancer gene in particular, BRAF or v-Raf murine sarcoma viral oncogene homolog B, encodes the protein B-Raf." (PMID 26312489, 2015). "The cancer risk in nodules with BRAFV600E mutation was 100%, significantly higher than that with wild-type BRAF (3.4%, P < 0.0001)." (PMID 26597052, 2015). "These follow a ‘traditional pathway’ in which key molecular events, such as mutations of APC and KRAS, have been previously well defined and result in cancers that are BRAF wild type and microsatellite stable." (PMID 25613750, 2015). "BRAF mutant cancers that had methylated PRDM5 were more likely to present at advanced stages compared to BRAF mutant cancers with unmethylated PRDM5 (AJCC stage III/IV: 29/65, 44.6% vs 31/105, 29.5%; p < 0.05)." (PMID 25613750, 2015). "BRAF-mutant cancer cells can negate antitumor effects of BRAF inhibition by activating different signaling pathways for cell survival and proliferation." (PMID 29061943, 2015). "Recent preclinical studies suggest a role for the Hippo signal transducer YAP in resistance to RAF and MEK inhibition in multiple cancer cell lines, including BRAF-mutant CRC." (PMID 26299805, 2015). "When the BRAF mutant cancers were stratified for MSI status, it was apparent that PRDM5 methylation correlated with CIMP." (PMID 25613750, 2015). "Fast and accurate diagnostic systems are needed for further implementation of precision therapy of BRAF-mutant and other cancers." (PMID 26330075, 2015). "Here we clearly provide evidence that the NRG-1β/ErbB-3 axis can induce the cancer stem cell compartment in tumors and induces their clonogenic capacity even in BRAF-V600E mutant CSCs." (PMID 26160848, 2015). "Previous data indicate that the CIMP-high subgroup, which exhibits a very high frequency of cancer-specific DNA hypermethylation, is strongly associated with epigenetic inactivation of MLH1 and BRAF mutation." (PMID 26530529, 2015). "These primary cultures contain both cancer stem cells (CSCs) and more differentiated cells and we observed that NRG-1β sustains proliferation and cancer stemness in both wild-type and BRAF-V600E mutant CSCs by activating the PI3K/AKT and ERK signaling axes." (PMID 26160848, 2015). "They enrolled 17 patients with advanced, biopsy-proven BRAF-mutant cancers, including melanoma, nonsmall cell lung cancer, and colorectal cancer." (PMID 26448936, 2015). "MEKi are potent targeted therapies designed to effectively shut off the MAPK signaling in cancers with activating mutations in RAS and BRAF." (PMID 26388333, 2015). "We further added to the complement of known RAS-activating mutations in observing mutations in BRAF (two MC), as well as previously unreported potentially RAS-activating alterations in FGFR2, ERBB2, and STK11, each affecting a single carcinoma." (PMID 25986173, 2015). "Here, the similarities but also the differential effects of RAS and BRAF oncogenic signalling are examined and further implications in personalized cancer diagnosis and therapy are discussed." (PMID 25361007, 2014). "Cell-biologic analyses were performed in order to link cancer cell traits to the BRAF-mutant genotype." (PMID 24885690, 2014). "One anaplastic cancer cell line, FRO, had a V600E mutation in BRAF and the three other cell lines had the wild type BRAF." (PMID 24727741, 2014).